E2F1 (E2F transcription factor 1)
Diseases named in the same sentence as E2F1 in open-access papers (continued):
Sharing a sentence is not in itself a finding about the gene and the disease.
tumor (continued). "E2F1 and ZBTB16 have been proved to belong to tumor-suppressive genes." (PMID 33083112, 2020). "Our findings indicate that Fucoidan- Sargassum reduced the expression level of E2F1 in the HCCLM3 cell line; therefore, Fucoidan- Sargassum may have inhibited tumor progression by leading the cancer cells to arrest." (PMID 31598149, 2019). "Key findings from our studies have identified E2F1, FOXM1, and ETS1 as coding gene/s axes that are overexpressed and may show strong involvement in tumor development in almost all cancer types." (PMID 30809433, 2019). "After analyzing the available association between E2F-1 and clinical data, it was revealed that E2F-1 expression was associated with tumor lymph node metastasis, and Tumor Node Metastasis (TNM) system, but not with age and tumor volume." (PMID 31278126, 2019). "E2F1 protein is activated to a greater extent in tumor tissues compared to that in the normal liver or adjacent non-tumor tissues from the same HCC patients." (PMID 31695969, 2019). "This study extends our knowledge about the regulation of proline synthesis and tumor progression by transcription factor and its derived lncRNA, and suggests that MZF1‐AS1/PARP1/E2F1 axis may be a therapeutic target for tumors." (PMID 31592410, 2019). "The genes most frequently showing CNGs in HAS tumour tissues were TOP1 (50.0%), STK4 (45.5%), CDKN1B (40.9%), H3F3A (36.4%), MYC (22.7%), CCNE1 (22.7%), NFKBIA (22.7%), VEGFA (18.2%), CCND3 (13.6%), and E2F1 (13.6%)." (PMID 30989433, 2019). "Except for few being chromatin regulators (CGBP, MBD2, and DNMT1), all of these TFs were found to have tumor suppressor functionality (BRCA1, E2F1&2&5&7, EGR1-4, FLI1, NRF1, TFDP2, and STAT1), or indirectly mediate the suppression of tumorigenesis and tumor suppressor activity (SP4 and ZBTB33)." (PMID 29740534, 2018). "The IHC analysis obtained from specimens derived from superior limb and parathyroid metastases of one patient whose tumor had progressed showed an increase of positive cells for HMGA1, E2F1, and vimentin supporting the role of HMGA1/E2F1 axis in MLS progression." (PMID 29980789, 2018). "Additionally, in vivo abemaciclib leads to a substantial reduction in tumor volume through downregulation of CDK4, CDK6, Cyclin D, Rb1, and E2F1 gene expression." (PMID 29245989, 2017). "Here we report a novel pathway involved in E2F1 and TINCR in tumor development and GC cell growth." (PMID 28569791, 2017). "Interestingly, thymoquinone inhibited the tumor growth of CRPC xenografts and repressed E2F-1 and AR expression." (PMID 28264478, 2017). "However, it is important to note that miR-106b/miR-93 also targets a wide range of tumor suppressor transcripts beyond PTEN, such as BIM, p21, and E2F1." (PMID 28212532, 2017). "Studies in human cell lines further investigated the physiologic targets of miR106a, and showed that miR106a could target tumor-suppressor genes, such as RUNX3, Twist1, pRB and E2F1." (PMID 27926519, 2017). "Moreover, a significantly decreased level of E2F1 and E2F3 was observed in tumor tissue of LLC mouse model with exposure to LF-MF." (PMID 28389657, 2017). "In contrast, all of the corresponding non-tumor tissues showed negative or weakly positive immunostaining of E2F1 protein." (PMID 27036039, 2016). "Mechanistically, Tspan5 suppresses the tumour growth through regulating the cell cycle transition from G1-S phase by increasing the expression of p27 and p15 and decreasing the expression of cyclin D1, CDK4, pRB and E2F1." (PMID 27223087, 2016). "The mRNA expression of E2F1 and ISX in 238 paired specimens from human HCC patients, and the adjacent, normal tissues exhibited a tumor-specific expression pattern which was highly correlated with disease pathogenesis, patient survival time, progression stage, and poor prognosis." (PMID 27175585, 2016).
tumor (continued). "The present study demonstrates that physical interactions between ARID2 and the transcriptional factor E2F1 play pivotal roles in ARID2-mediated suppression of cyclin D1 and cyclin E1, supporting the notion that ARID2 acts as a tumor suppressor by targeting the Rb-E2F signaling pathway." (PMID 27351279, 2016). "We found that cZNF292 silencing decreased the transcriptional activity of E2F1, NF-κB, Sp1, HIF-1, AP-1, STAT3, and STAT5 in the U87MG and U251 cell lines, suggesting that cZNF292 silencing represses tumor tube formation through altering transcription factor activity." (PMID 27613831, 2016). "One possible function could be the inhibition of E2F transcription factor 1, E2F1, a putative tumour suppressor gene." (PMID 26465597, 2015). "Genome expression profiles were highly different in S6K1 and S6K2 high tumours, whereas S6K2 and 4EBP1 profiles showed significant overlaps, both correlated to genes involved in cell cycle progression, among these the master regulator E2F1." (PMID 26698305, 2015). "In contrast to PUF60, the BOP1 and E2F1 were found to be over-expressed in tumor tissues with copy number gains as well as in those without." (PMID 26360582, 2015). "Our finding on the repression of SIRT6 transcription by E2F1 will broaden the therapeutic opportunities to enhance SIRT6 tumor suppressor activities with compounds like CDK4/6 inhibitor, which retains E2F1 in the RB-E2F1 complex by diminishing the phosphorylation of RB by CDK4/6." (PMID 25816777, 2015). "The PHx-induced tumors as compared to spontaneous tumors were enriched with the “Oncogene”, “CIN” and “E2F1”, but not with “Tumor suppressors”, signatures." (PMID 25401338, 2014). "It was observed that expression of ICAM-1 in DU145/sh-E2F1 tumors was higher than control and DU145/sh-ICAM-1 tumors, indicating that the increase in ICAM-1 expression is correlated to suppression of DU145 xenograft tumor growth by E2F1 knockdown." (PMID 24742333, 2014). "However, measurements of motif activity correlation with mRNA expression of the TFs shows that the expression of E2F1, E2F2 and E2F8 exhibit the most significant correlation with E2F motif activity in the time course and tumor studies." (PMID 24464994, 2014). "Overall, these cells were rare and our analysis shows that E2f1 is able to largely rescue both the tumor and developmental phenotype, E2f3 is able to rescue the tumor phenotype but not the developmental phenotype and E2f5 can rescue neither." (PMID 25338120, 2014). "Furthermore, silencing E2F1 increases ICAM-1 mediated leucocytes infiltration and inhibits tumor growth in vivo." (PMID 24742333, 2014). "E2F1 expression was significantly higher in tumor group than in noncancerous tissue group (p<0.001)." (PMID 24023875, 2013). "FAM60A is also implicated in the tumorigenesis process through protein-DNA interaction with E2F1 (E2F transcription factor 1) and finally, DDX55 expression is indirectly controlled by SOD2(superoxide dismutase 2, mitochondrial), which is directly involved in neoplasia and carcinogenesis." (PMID 22280244, 2012). "In this report, we show that E2F1 and STAT1 are activators of MUC4 mucin tumor marker." (PMID 22537161, 2012). "Notably, while E2F1, Ki-67 and TOP2A transcript levels areall cell-cycle regulated, we generally observed E2F1 immunostaining in a largerproportion of tumor cells, in contrast to Ki-67 and TOP2A, which stained only aminority fraction of cells." (PMID 21629784, 2011). "Such elevations in E2F1 and E2F7 are clearly pathologic and the consequences on UV-induced tumour development and progression remain unknown." (PMID 22272113, 2011).
tumor (continued). "The data indicate that both E2F1 and E2F2 could be highly expressed in tumor tissues correlating with elevated expression of KDM5B (Spearman's rank correlation coefficient: r = 0.666 [E2F1] and r = 0.756 [E2F2], respectively)." (PMID 20226085, 2010). "In HT-29 and THP-1 tumor cells an up to 15% reduction of mRNA expression for both genes (E2F-1 and PCNA) compared to control without treatment was detectable." (PMID 19551155, 2009). "Interestingly, E2F1, E2F3 and E2F5 were present on this supervised gene list and highly expressed in tumours with RB1 LOH." (PMID 18782450, 2008). "It is important to determine the repressive effects of E2F-1 on hTERT transcription in tumor cells with and without the normal BRCA1 protein to determine any variance between BRCA1 status and inhibition of telomerase." (PMID 18366791, 2008). "Furthermore, the progressive suppression of ASCC2, ALKBH3, E2F1, and G6PD led to a marked decrease in their immunohistochemical staining scores, indicating reduced protein expression and altered cellular localization within the tumor microenvironment." (PMID 41484982, 2026). "Furthermore, the reduced levels of L-lactic acid slow tumour progression through histone H4K16 lactylation and regulate the expression of the BEST1, GRAMD4, and MBD6 genes, with this mitochondrial effector serving as an apoptotic signal induced by E2F1." (PMID 41249152, 2025). "Further, by assessing changes in histone modifications in the CDKN1A promoter region, which regulates the E2F1 transcription factor, we determined that ARID1A deletion downregulates CDKN1A acetylation, diminishes P21 protein transcription, and initiates a cascade of tumor drug resistance responses." (PMID 38600891, 2024). "LncRNA PLANE (Pan-cancer LncRNA Activating NCOR2 responsive to E2F1) is up-regulated by copy number gain and E2F1-driven transcription activation, and then combines with NCOR2 pre-mRNA to modulate its alternative splicing, finally drives tumorigenesis and tumor propagation in various tumor types." (PMID 38933287, 2023). "E2F1 is also high in qISC, where it might exert its known role as repressor of OXPHOS and mitochondrial function and promote FAO to support self-renewal and drug resistance via NANOG in tumor-initiating stem-like cells." (PMID 35448502, 2022). "Finally, xenograft transplantation validated that E2F1 inhibition could suppress LY294002, thereby discouraging tumor growth." (PMID 35592867, 2022). "In addition, the potential of PRR11 to initiate tumor cell proliferation and migration in ccRCC depends on the novel function of the classic transcription factor E2F1." (PMID 34499617, 2021). "Additionally, E2F1 and SKP2 are highly expressed in multiple tumour cells collaboratively." (PMID 34428336, 2021). "Furthermore, the varying read support seen for confirmed translocations indicates a high amount of tumor heterogeneity occurring in both models, regardless of E2F1 status." (PMID 33947907, 2021). "Although MYC and E2F1 are two well-studied oncogenic transcription factors that are frequently dysregulated in PCa cells, whether the two genes together with TERT have synergistic effects on tumor severity are still unclear." (PMID 34858826, 2021).
tumor (continued). "Hence, a combination of inhibitors blocking both pathways could lead to a significant tumor growth reduction together with a decrease in proliferation indexes, including RB1 phosphorylation, E2F1, CCND1, and PCNA expression levels, in the NPC PDX model." (PMID 34204797, 2021). "Previously, we reported that Tspan5 is downregulated in gastric cancer tissues and functions as a tumour suppressor in stomach to control the tumour growth by regulation of cell cycle transition from G1‐S phase via decreasing the expression of cyclin D1, CDK4, pRB and E2F1." (PMID 33955149, 2021). "Furthermore, through analysis of gene expression levels in tumor and normal samples and survival analysis, CXCL8, KIF18A, and E2F1 showed high expression and poor prognosis, which indicated that they may play a role in promoting ESCA progression." (PMID 32851080, 2020). "More than merely sustaining the Warburg phenotype, the establishment of a coherent feedforward loop within the SLC16A1-AS1:E2F1/SLC16A1/MCT1 regulatory axis rewires E2F1 with lipid and mitochondrial metabolism, i.e. two metabolic traits that are emerging as essential factors of tumor progression." (PMID 32863950, 2020). "Many studies have confirmed that E2F1 could activate the expression of stromal markers related to EMT such as vimentin and fibronectin and facilitate the pathogenesis processes such as fibrosis and tumor progression." (PMID 32596346, 2020). "RT-PCR analysis of the transcriptional expression of cell cycle genes showed a significantly increased expression of ccnA1, ccnB2, ccnD3, ccnE1, cdc25b, and E2F1 and a significantly decreased expression of ccnD2 in the Fhit-transfected versus non-transfected tumor cells." (PMID 32545680, 2020). "Thus, fast replicating tumor cells preferentially express E1A under E2F-1 promoter as compared to no-replicant normal cells." (PMID 33066689, 2020). "In this cross-sectional descriptive study, we evaluated the expression of E2F1, MYC, and miR-17-5p by quantitative real time PCR analysis in 60 PitNETs: 29 gonadotroph (GT), 15 functioning somatotroph (ST), and 16 corticotroph (CT) tumours, of which 8 were silent (sCT)." (PMID 32316225, 2020). "Indeed, studies using mouse models of RB have shown that tumor initiation in the absence of RB requires E2F1, thus supporting the idea that the repression of E2F1 target genes is behind the tumor suppression activity of RB." (PMID 28812991, 2017). "However, E2F1 gene expression was 4-fold greater on tumor compared to normal tissue of patient #2, who presented a somatic mutation at the MIR136-5p target site." (PMID 28704519, 2017). "However, even if preliminary, these results indicated that the chimeric protein could retain DNA binding specificity of SRF and through the trans activation domain of E2F1 is able to activate SRF target genes, probably supporting tumor growth." (PMID 28947952, 2017). "Some previous studies support the role of E2F1 as a tumour suppressor rather than an oncogene." (PMID 27835866, 2016). "Based on these previous observations, it was considered that the downregulated miR-330 expression observed in the pre-treatment OAC biopsies from non-responders potentially induces the E2F1/p-Akt cell survival pathway, thereby promoting tumour resistance to CRT." (PMID 26221725, 2015). "An additional E2F1 target regulated by miR-10b, EZH2, is the catalytic subunit of Polycomb Repressor complex 2, overexpressed in various malignancies, including GBM, that inhibits differentiation, activates cell cycle, increases cell motility, and enhances self-renewal and tumor initiating capacity." (PMID 25738367, 2015). "The prognostic value of S6K2 and/or 4EBP1 in IGFR/HER2 positive tumours could be confirmed in two additional public datasets, and was also independent of the strong proliferation marker E2F1." (PMID 26698305, 2015).
tumor (continued). "To investigate whether POH1 regulates E2F1 ubiquitination, we first examined the levels of polyubiquitin-modified E2F1 in tumour cell lines with or without POH1 knockdown." (PMID 26510456, 2015). "Importantly, E2F1, E2F2 and E2F8, previously identified as strong candidate regulators of early PB-mediated transient hyperplastic response, display similar positive correlation between their gene expression and the motif activity in the tumor." (PMID 24464994, 2014). "Such duality in the role of E2F-1 in the testis might explain why its level appears diminished in "runaway" seminomatous tumours of testis (data not submitted)." (PMID 17147820, 2006). "Since ERE73s-ARF (−13) constructs showed lower promoter activity than the E2F1 promoter in all cancer cell lines tested, we wanted to determine whether activity of ERE73s-ARF (−13) constructs is sufficient to drive HSV-TK gene expression and suppress tumor growth in vivo." (PMID 41439972, 2025). "ETS1, though not in our list of significantly differentially expressed gene across all tumor types, regulates at multiple levels: at the level of E2F1, FOXM1 and PVT1, but due to its negative immunoreactivity in all tumor types, it may be doing so at gene/mRNA level." (PMID 30809433, 2019). "Moreover, statistical analysis indicates that the level of E2F1 was related to T stage, tumor differentiation, lymph node metastasis, and clinical stage, rather than age and tumor primary locations." (PMID 31801947, 2019). "The results showed that the expression levels of E2F2, E2F3, E2F6, and E2F8 are significantly correlated with the tumor stage of PAAD patients, while the expression levels of E2F1, E2F4, E2F5 and E2F7 are not correlated with the tumor stage of PAAD patients." (PMID 33604289, 2020). "Western blotting of fresh-frozen re-grafted tumor lysates showed that JQ1 treatment did not suppress MYCN or Brd4 protein expression in the tumors, but clearly downregulated E2f1 protein expression." (PMID 25174395, 2015). "Whereas the absence of E2F1 and E2F3 function has no impact on Myc-mediated tumor development, the absence of E2F2 substantially accelerates the time of tumor onset." (PMID 19749980, 2009). "We chose 4 genes (KIF25, E2F1, DIP2C, TFG) that were present in at least 4 tumor patients, were not present in the healthy population, were detected outside of patients 18, 19, 30, 34, and 38, and have the potential to serve as therapeutic targets or diagnostic and predisposing biomarkers." (PMID 38982214, 2024). "This is consistent with our findings that E2F1, but not E2F8 KD induced tumor cell apoptosis." (PMID 38686617, 2024). "Silencing of E2F1 by long non-coding RNA could suppress tumor growth in LUAD patients, but the downstream target genes of E2F1 were not clear." (PMID 34650921, 2021). "E2F1 bound to RASSF1A and BLU genes in the MRC5 normal cell line, but not in A549 tumor cell line." (PMID 20877461, 2010). "Moreover, we also found higher expression levels of both E2F1 and E2F2 in clinical tumor tissues where KDM5B was overexpressed, than in non-neoplastic tissues (P = 0.0009 and P = 0.0002, respectively)." (PMID 20226085, 2010). "However, overexpression of TFDP1 did not correlate with altered expression levels either of its protein partner, E2F1, or one of the E2F1/TFDP1 regulators, RB, in our tumor cohort (data not shown)." (PMID 19995430, 2009). "Pull-down using an E2F1 antibody showed enrichment of E2F1 at a consensus-binding site within the Hells promoter in samples that highly express HELLS protein: P0 wild-type and P21 Rb1/p107 DKO retinae and human tumor cells, but not in P21 Cre-negative Rb1/p107." (PMID 32071286, 2020).